EGFR (epidermal growth factor receptor)
Diseases named in the same sentence as EGFR in open-access papers (continued):
Sharing a sentence is not in itself a finding about the gene and the disease.
colon carcinoma (continued). "We aimed to examine the efficacy of anti-epidermal growth factor receptor (EGFR) treatment for middle/low rectal and left-sided colon cancers." (PMID 34188197, 2021). "Flavonoids induce apoptosis and suppress the growth of colon cancer cells by inhibiting the COX2- and Wnt/EGFR/NFκB-signaling pathways, which play crucial roles in CRC." (PMID 34394377, 2021). "H3K36me2, expressions of multiple oncogenes (ADAM9, EGFR, Sox2, Bcl-2, SYK, and MET) and Akt activation were significantly decreased after NSD2 silencing or knockout in primary colon cancer cells." (PMID 34671018, 2021). "The classic and most studied signaling pathway is EGFR pathway since both COX-2 and PGE2 are involved in the proliferation, migration and invasion of human colon carcinoma cells through EGFR." (PMID 32363546, 2020). "The therapeutic mAB cetuximab, an epidermal growth factor receptor inhibitor, is approved for the treatment of locoregionally advanced and recurrent/metastatic HNSCC and colon carcinoma." (PMID 32466374, 2020). "In another colon cancer cell line (SW480), EGCG induced the phosphorylation of p38, which mediated the phosphorylation of EGFR at Ser1046/1047, leading to a downregulation of the EGFR/MAPK pathway." (PMID 31979082, 2020). "In colon cancer, PAR2 enhanced cancer cell growth through the signaling axis consisting of PAR2, MMPs, TGF-α, EGFR and ERK." (PMID 32365084, 2020). "This issue has been addressed in several preclinical and clinical studies, which indicate that EGFR blockade and BRAF targeting act synergistically to inhibit ERK pathway signaling in BRAFV600E mutant colon cancers." (PMID 32066410, 2020). "Anti-EGFR monoclonal antibody is recommended for RAS–wild or left colon cancers, and VEGF antibody is recommended for RAS-mutant or right colon cancers." (PMID 32708359, 2020). "In this in vitro study, we determined the reversal efficacy of the epidermal growth factor receptor (EFGR) inhibitor, saptinib, in SW620 and SW720/Ad300 colon cancer cells and HEK293/ABCB1 cells which overexpress the ABCB1 transporter." (PMID 33163405, 2020). "EGCG inhibition of EGFR and HER2 was demonstrated in colon cancer cells line (HT29), in which these proteins are overexpressed in comparison with normal tissue." (PMID 31979082, 2020). "In conclusion, the present study represents a comprehensive analysis of the global alterations of ATG genes in a broad range of cancer types, with emphasis on the roles of EGFR and RARA in colon cancer cells." (PMID 31896739, 2020). "CUR was found to suppress the expression of EGFR, mediated by the reduction of Egr-1 activity in Caco2 and HT29 colon cancer cells, inhibiting colon cancer cell growth." (PMID 30890933, 2019). "Several studies showed that post-EGFR pathways are involved in promoting cell migration, including the MEK/ERK1/2 pathway in colon cancer cells, or the PI3K/AKT signaling pathway in NSCLC." (PMID 30925742, 2019). "NINJ2 co-immunoprecipitated with multiple RTKs (EGFR, PDGFRα/β and FGFR) in CRC cells and human colon cancer tissues." (PMID 31597121, 2019). "Suppresses the expression of EGFR, mediated by the reduction of Egr-1 activity in Caco2, and HT29 colon cancer cells, inhibiting colon cancer cell growth." (PMID 31801262, 2019). "As shown, in both HT-29 cells and primary human colon cancer cells (“pri-Can-1”), NINJ2 co-immunoprecipitated with EGFR, PDGFRα, PDGFRβ and FGFR." (PMID 31597121, 2019). "Here we show that VEGFR-1 interacted with and stabilized epidermal growth factor receptor (EGF-R), leading to an increased EGF-R-dependent proliferative activity of colon cancer cells." (PMID 31717527, 2019). "This nanocomposite exhibited pH and NIR triggered drug release, which resulted in effective inhibition of colon cancer cells (DLD-1, exhibiting overexpression of EGFR) due to synergistic chemo and photothermal therapy." (PMID 29881657, 2018).
colon carcinoma (continued). "In HT-29 colon cancer cell lines deprived of epidermal growth factor (EGF), it was seen that EGFR is mainly located at in Ld domains but upon activation with EGF or TGFα, EGFR translocates to Lo domains, to produce its downstream signaling." (PMID 30518103, 2018). "NK cells are capable to lyse primary colon cancer cells independently of the RAS, BRAF and EGFR status, but this effect is enhanced in combination with cetuximab in EGFR-positive cells through the activation of ADCC." (PMID 30567306, 2018). "Our laboratory has previously shown that PEG downregulates EGFR in both AOM-treated rat and human colon cancer cells, HT-29." (PMID 29617381, 2018). "This interaction between ERRα and EGFR suggests a potential novel function of ERRα in the EGF-mediated survival and proliferation of colon cancer cells." (PMID 30185207, 2018). "Here we report the development of novel EGFR inhibitors, having pro-apoptotic and tumor suppressive effects in wild-type KRAS colon cancer." (PMID 30158525, 2018). "Studies in colon cancer revealed that M3R was able to promote MMP7 to catalyze the release of HB-EGF and thus facilitate ACh-induced EGFR signaling activation." (PMID 28102288, 2017). "In the HT29 and SW80 colon cancer cell lines the treatments of EGCG also inhibited the ErbB2 and EGFR activity." (PMID 28286519, 2017). "In conclusion, NCTD suppressed the phosphorylation and expression of both EGFR and c-Met in HCT116 and HT29 human colon cancer cells." (PMID 28086832, 2017). "When SIRT1-Flag tagged expression plasmid was transfected into Human colon cancer HCT116 cell line, the acetylation levels of SMARCA5, MTA2, HMGA1, EGFR, CHD4 and GOT2 decreased as equal amounts of the proteins were immunoprecipitated." (PMID 28676654, 2017). "Here, we wanted to identify RTKs that were potentially activated during treatment with the monoclonal antibody EGFR inhibitor cetuximab in previously identified intermediate cetuximab-sensitive KRAS and BRAF wild-type colon cancer cell lines." (PMID 28032592, 2017). "Co-inhibition of EGFR and MET promotes eradication of colon cancer stem cells, resulting in durable tumor regression." (PMID 28420162, 2017). "To determine the potential interaction between panitumumab and FTD in EGFR signaling, we analyzed the phosphorylation status of signaling mediators ERK and AKT in FTD‐treated colon cancer cells using western blotting." (PMID 28486761, 2017). "Three different cell lines of colon cancer origin were compared, i.e., COLO320 (EGFR− RASwt), SW480 (EGFR+ RASmut), and HT-29 (EGFR+ RASwt BRAFmut)." (PMID 28220124, 2017). "As MAPK and PI3K play a central role in transduction of signals from EGFR, and the activation of Ras/Raf/MAPK pathway induces AREG transcription in colon cancer cells, we examined if EGF induce AREG through these pathways." (PMID 27669890, 2016). "It is conceivable that the inhibitory effect of AUY922 on multiple protein kinases such as CRAF and EGFR would also contribute the combinatorial effect of HSP90 inhibitors and BRAF inhibitors in colon cancer cells." (PMID 27391062, 2016). "Structural variations were relatively infrequently to find three cases of CDKN2A, ERBB2 and EGFR amplification and single one RET-NCOA fusion in a young patient with sporadic, left colon cancer (MSI-S)." (PMID 26909603, 2016). "FLAG-tagged PGRMC1 ectopically expressed in human colon cancer HCT116 cells was immunoprecipitated with anti-FLAG antibody, and co-immunoprecipitated EGFR and endogenous PGRMC1 binding to FLAG-PGRMC1 were detected by Western blotting." (PMID 26988023, 2016). "Specifically, in human colon carcinoma cells, the authors showed that deacetylation of SP1 by HDAC3 results in increased binding of SP1 to the EGFR promoter." (PMID 26243279, 2015). "The migration of colon cancer cells can be inhibited by AQP3-specific inhibitor, as well as EGFR pathway inhibitors." (PMID 25886458, 2015).
colon carcinoma (continued). "We demonstrated that in human colon cancer cell lines, upon AhR activation by TCDD, Src-mediated cross-talk between AhR and EGFR results in ERK1/2 activation and enhanced cell proliferation." (PMID 26264025, 2015). "Consistent with previous findings, we found that EGFR inhibitor gefitinib alone modestly decreased the cell viability in SW1116 and PC-9 colon cancer cell lines carrying wild-type EGFR gene." (PMID 24874286, 2014). "In EGFR TKI erlotinib-resistant lung cancer cells and colon cancer cells, the induced insulin-like growth factor-I receptor activation is implicated in resistance to erlotinib." (PMID 24714091, 2014). "Our preclinical evaluation of genistein-derived EGFR inhibitors suggests that these compounds are much more potent sensitizers of cells to radiation than the parent isoflavonoid, genistein and indicate that these compounds may be useful in the treatment of colon cancer with radiation therapy." (PMID 25401399, 2014). "Contrary to resistance against EGFR and ERBB2 targeting, the genetic inhibition of ERBB3 results in anti-tumorigenic in HCT116 colon cancer cells harboring constitutively active KRAS and PIK3CA mutations." (PMID 24970817, 2014). "The EGFR transactivation by PAR1 or PAR2 leading to COX-2 expression, enhanced cell proliferation in colon carcinoma cells and cell migration in renal carcinoma cells is dependent on matrix metalloproteinase (MMP) activity." (PMID 24215724, 2013). "With respect to the progression of colon cancer, this mechanism includes PAR2-mediated EGFR transactivation and a subsequent increase of COX-2 expression in colonic epithelial cancer cells." (PMID 24215724, 2013). "In PEG-induced colon cancer chemoprevention, we have previously shown that cell cycle arrest induced by PEG-8000 implicates an EGFR-mediated upregulation of a cyclin-dependent kinase inhibitor, p21cip1/waf1." (PMID 22675506, 2012). "Herein, we report the novel observations that in human colon cancer cells Src kinase mediates cross-talk between FXR and EGFR, thereby controlling cell proliferation." (PMID 23119029, 2012). "For example, in mouse models of CRC and several human colon cancer cell lines including H508 and SNU-C4 cells used in this study, we showed that cholinergic muscarinic receptors cross-talk with EGFR to stimulate cell proliferation, tumor growth and invasion." (PMID 23119029, 2012). "Zhou and Brattain demonstrated synergy between EGFR and HER2 tyrosine kinase inhibitors towards the induction of apoptosis in human colon cancer cell lines." (PMID 22988345, 2012). "Collectively these data support the novel conclusion that in human colon cancer cells Src-mediated cross-talk between FXR and EGFR modulates ERK phosphorylation, thereby regulating intestinal cell proliferation and tumorigenesis." (PMID 23119029, 2012). "Collectively, these findings demonstrate that, downstream of EGFR activation, bile acid-induced PI3K/AKT and NF-κB activation regulate colon cancer cell apoptosis and survival." (PMID 24212649, 2011). "For instance, EGFR activation results in PTGS2 (COX-2) expression at both mRNA and protein levels in a rat intestinal epithelial cell and colon cancer cells in vitro." (PMID 24213116, 2011). "In thisstudy, we demonstrated that both EGFR mRNA and its promoter activity were inhibitedby HDAC inhibitors in colon cancer cells, indicating that the denovo synthesis of EGFR was transcriptionally inhibited." (PMID 21464950, 2011). "The positivecorrelation between EGFR and HDAC3 expression was also observed in fourteenpairs of human colon tumor and adjacent normal tissues." (PMID 21464950, 2011). "In this report, we determined the prognostic effect of EGFR expression in relation to its activation status in primary stage II and III colon carcinomas from patients treated in 5-fluorouracil-based adjuvant therapy trials." (PMID 19997103, 2010).
colon carcinoma (continued). "Epidermal growth factor receptor (EGFR) protein expression, evaluated by immunohistochemistry (IHC), has been shown to have prognostic significance in patients with colon cancer." (PMID 20842128, 2010). "Epidermal growth factor receptor (EGFR) antagonists and monoclonal antibodies were found to have promising results in non-small lung cancer and colon cancer." (PMID 20961443, 2010). "Accordingly, we analysed phospho-EGFR and EGFR expression in a large series of stage II and III colon cancers from completed 5-fluorouracil-based adjuvant therapy trials." (PMID 19997103, 2010). "Phospho-EGFR (Tyr-1173) and EGFR expression were analysed by immunohistochemistry (IHC) in tissue microarrays of TNM stage II and III colon cancers from completed adjuvant therapy trials (n=388)." (PMID 19997103, 2010). "Anticancer drugs aimed at molecular regulators, including epidermal growth factor receptor (EGFR or HER1), its homologue c-erb-2 (HER2), have been developed and shown to be effective in the breast, lung, and colon cancers." (PMID 19223902, 2009). "The tumors here investigated were selected based on potential EGFR treatment, which may bias the results toward tumors prone to metastatic development, though the overall KRAS mutation frequency of 39% and the relation between colon cancer and rectal cancer are as expected." (PMID 19832985, 2009). "In the HT29 human colon cancer cells, EGCG and Poly E inhibit the activation of EGFR and HER2, the phosphorylation of Akt and ERK proteins, and also the transcriptional activity of the AP-1 and NF-κB promoters." (PMID 19325845, 2008). "In order to verify that EGFR signaling was intact in our cells, the effects of EGF treatment on the expression and activation of EGFR and ERK1/2 in HT29 human colon cancer cells was examined." (PMID 16138927, 2005). "Accordingly, we hypothesized that EGFR may be downstream of SLC5A1, affecting colon cancer cell migration and invasion." (PMID 39781340, 2025). "To determine whether the cytotoxic activity of rTBL-1 is dependent on EGFR in the cellular system, we evaluated the effect of a range of concentrations between 0 and 100 μg of rTBL-1/mL in two colon cancer cell types: MC-38 cells, EGFR+, and CT-26, EGFR−." (PMID 40006027, 2025). "In this work, we evaluated the ability of rTBL-1 to produce apoptosis in two murine colon cancer cell lines, with and without EGFR expression." (PMID 40006027, 2025). "In this study, selective induction of Gal-9, but not of other galectins, was also observed in vitro across a broad panel of EGFR-wild-type and mutant human and murine NSCLC, lung, and colon cancer cells treated with the EGFR-TKIs, osimertinib, erlotinib, gefitinib, or afatinib." (PMID 40869319, 2025). "In colon cancer, KRAS mutation has been identified as a strong negative predictive biomarker that confers resistance to EGFR inhibitors." (PMID 41523436, 2025). "Our findings indicate that the ability of Hesperidin to prevent colon cancer may depend on the suppression of SLC5A1 expression, which inhibits EGFR phosphorylation." (PMID 39781340, 2025). "In addition, when used in combination with cetuximab, TH downregulates epidermal growth factor receptor (EGFR) expression, thereby inhibiting colon cancer cell proliferation." (PMID 40298838, 2025). "Reg IV may also promote carcinogenesis by activating the epidermal growth factor receptor (EGFR), as Reg IV is a strong stimulator of the EGFR/Akt/activator protein-1 (AP-1) signaling pathway in colon cancer cells." (PMID 39421174, 2024). "Growth factors like epidermal growth factor receptor (EGFR) are crucial for CRC cell proliferation, and using EGFR ASO encapsulated in PAMAM nanoparticles has been shown to reduce the proliferation of the human colon cancer cell line HT29." (PMID 39857631, 2024). "Similarly, in colon cancer, overexpression of FGFR4 triggers AREG secretion, which promotes tumor growth through EGFR phosphorylation at Tyr1068." (PMID 39451251, 2024).
colon carcinoma (continued). "For example, miR-19a inhibits colon cancer angiogenesis by targeting KRAS and VEGFA, and miR-181d reduces cell proliferation, migration, and invasion by triggering PEAK1, a downstream regulator of the EGFR/KRAS pathway." (PMID 36960218, 2023). "However, many of the signalling pathways regulated by membrane oestrogen actions in colon (EGFR, ERK-MAPK, PI3K-Akt, and Wnt) are involved in cell proliferation, survival, and migration in colon cancer cells." (PMID 38137047, 2023). "This negative feedback mechanism is similar to the EGFR feedback activation by verofenib in colon cancer and by lomvartinib in hepatocellular carcinoma." (PMID 36678567, 2023). "Also, miR-145-5p overexpression was shown to downregulate RHBDD1 by inhibiting EGFR-related signaling pathways (EGFR/Raf/MEK/ERK axis), thereby inhibiting colon cancer tumorigenesis." (PMID 36960218, 2023). "Here, we found that GALNT2 knockdown suppressed the activity of EGFR and MET in colon cancer cells." (PMID 36409270, 2023). "Similarly, the restoration of miR-143-3p levels in combination with an EGFR inhibitor reduced AKT levels and inhibited the growth of K-Ras-driven colon cancer cells." (PMID 37759434, 2023). "Both EGFR and HER2 have a role in colon cancer metastasis and development." (PMID 37631234, 2023). "This is in contrast to adjuvant clinical data which show that anti-EGFR antibodies, but not EGFR small molecule inhibitors, are effective in colon cancer." (PMID 37169023, 2023). "The results showed that many cancer-related pathways were enriched in high-risk groups such as cellular response to hypoxia, glycolysis and gluconeogenesis, metabolic reprogramming in colon cancer, APC mediated degradation of cell cycle proteins, signaling by EGFR." (PMID 36077637, 2022). "Thiosemicarbazones have been reported to downregulate EGFR expression and phosphorylation in pancreatic and colon cancer cells; however, we did not detect any alterations in EGFR activity after treatment with DpC." (PMID 36160437, 2022). "A prominent example is the epidermal growth factor receptor (EGFR), which besides being overexpressed in colon cancer, is also present in non-malignant tissues including skin, liver and kidney." (PMID 35073465, 2022). "Although it may seem paradoxical, our results suggested that SLC25, and in particular, SLC25A5 and SLC25A24, might be involved in the EGFR and ERK-MAPK signaling pathways in colon cancer and potentially serve as treatment targets." (PMID 35288533, 2022). "Furthermore, the expression of EGFR and MITF are inversely correlated in melanoma and forced expression of MITF in melanoma and colon cancer cells inhibits EGFR expression." (PMID 35406721, 2022). "Ultimately, based on our MCIA, we identified CD15, CD104 (Integrin-β4), CD324 (E-cadherin), CD326 (EpCAM), and CD49f as biomarkers for colon cancer and CD24, CD26 (DPP4), CD106 (VCAM1), TIM-1, SSEA-3 (B3GALT5), SSEA-4 (TMCC1), TRA-1-60-R (PODXL) and EGFR for renal cancer." (PMID 36221114, 2022). "Secondary BAs, such as DCA, initiate proliferation and invasion of colon cancer cells through activation of COX-2, epidermal growth factor receptor (EGFR), extracellular signal-regulated kinases 1 and 2 (ERK1/2), activator protein 1 (AP1), c-Myc, and NF-kB at very low concentration." (PMID 35178126, 2022). "Loss of CAV1 was frequently observed in various types of malignancies including colon cancer, in which CAV-1 silencing results in activation of multiple survival signals including Src, EGFR, HER2, and the mitogen-activated protein kinase cascade and promotion of cancer transformation and initiation." (PMID 35163100, 2022).